CCL2 (C-C motif chemokine ligand 2)
Diseases named in the same sentence as CCL2 in open-access papers (continued):
Sharing a sentence is not in itself a finding about the gene and the disease.
tumor (continued). "Recent studies have demonstrated that CCL2 acts directly (via CCR5) in an autocrine manner on several human carcinomas regulating the migration and invasive properties of tumour cells." (PMID 22353646, 2012). "While anti-CCL2 MAb prevented the migration of the monocytes to the tumor site, TMZ probably played a role in surveillance and killing of monocytes that reached the tumor site, thereby mitigating immune suppression." (PMID 23133490, 2012). "Recombinant mouse CCL2 (MCP1) was used as a representative CCR2 ligand, which plays a pivotal role in the recruitment of monocytes at tumor sites." (PMID 22952881, 2012). "Tregs can be significantly reduced in mice with antimurine CCL2/CCL12 monoclonal antibodies, resulting in significant reductions in Treg cells in the spleens and tumours." (PMID 22778767, 2012). "We show that the administration of CCR2-Ig that selectively neutralize CCL2 entirely suppress tumor development in CCR2−/− mice, where the only cells that were CCR2+ were the tumor cells." (PMID 22279523, 2012). "Together, these findings indicate that there was high incidence of CCL2, CCL5, TNFα and IL-1β expression in the tumor cells in the three groups of cancer patients, and that the expression of TNFα and IL-1β was further elevated in the IDC-with-relapse group." (PMID 21486440, 2011). "CCL2, CCL5, TNFα and IL-1β were expressed at very low incidence in normal breast epithelial cells, but their incidence was significantly elevated in tumor cells of the three groups of cancer patients." (PMID 21486440, 2011). "Thus, inhibiting CCL2 or its receptor may allow a direct interference with tumor biology." (PMID 21943176, 2011). "Previously, it was shown that 4T1 cells produce various chemokines, including CCL2, CCL3, CCL4 and CCL5, that we also detected in the tumor microenvironment, with CCL5 levels being significantly higher in tumors in α-TEA-treated mice." (PMID 21232138, 2011). "Our data suggest that CCL2 secreted by tumor cells and CCR2 receptors on CTLs are involved in migration of CTLs towards tumor." (PMID 21450101, 2011). "Among the many chemokines expressed in the tumor micro-environment, CCL2 (or monocyte chemotactic protein-1) occupies a prominent role and has been selected for therapeutic purposes." (PMID 24213109, 2011). "While it has been reported that CCL2, CXCL1 and CXCL5 are important for tumour growth, proliferation, and angiogenesis, the effect of these chemokines on DCs has not previously been documented." (PMID 22125641, 2011). "Pre-clinical studies have shown that anti-CCL2 antibodies or antagonists to its receptor CCR2, given in combination with chemotherapy, were able to induce tumor regression and yielded to improved survival in prostate mouse cancer models." (PMID 24213109, 2011). "Intrahepatic lymphocytes, isolated from non-tumor tissue, were stimulated with peptides overnight and culture supernatants were screened for CXCL-8, CXCL-9, CXCL-10, CCL-5, CCL-2 as well as IL-17 and the anti-inflammatory cytokine IL-10." (PMID 21876747, 2011). "Major attractants of monocytic cells are the CC chemokines and in a variety of cancers, CCL2 and CCL5 levels are highly correlated with high numbers of intra-tumor myeloid cells, particularly TAM." (PMID 24212934, 2011). "The recruitment of immature myeloid cells is enhanced by the production of chemokine (C–C motif) ligand-2/monocyte-chemotactic protein-1 (CCL-2/MCP-1), which is produced and expressed by TAMs and tumour cells." (PMID 20664588, 2010). "Some data indicate that chemokines, such as IL-8 (CXCL8), MCP-1 (CCL2), and RANTES (CCL5), not only stimulate migration, but also proliferation of tumor and stromal cells, including endothelial cells." (PMID 18728788, 2008). "Given that CCL2, GM-CSF, and CXCL8 primarily function within the tumor microenvironment, we expected that other N4BP1 targets might directly affect cancer cells." (PMID 41513619, 2026).
tumor (continued). "Additionally, hsa_circ_0110,102 sponges miR-580-5p to downregulate PPARα and inhibit CCL2 secretion, subsequently suppressing the release of pro-inflammatory cytokines from macrophages via the COX-2/PGE2 pathway, exerting a tumor-suppressive effect." (PMID 41602547, 2026). "In contrast, non-amplified tumors exhibit higher levels of CCL2, which attracts both anti-tumor immune cells such as DCs and macrophages, as well as pro-tumor populations including Tregs and tumor-associated macrophages (TAMs)." (PMID 41936749, 2026). "As a result, the two Gemini-like NPs in hydrogel cut CAF-secreted CCL2 by 72%, reduced CD44+CD133+ CSCs by 68%, and tripled intratumoral granzyme-B+ CD8+ T cells, yielding almost complete tumor regression in 90% of mice (n = 10), which achieved a remarkable regression of the chemo-resistant tumors." (PMID 41355964, 2026). "In our study, the dose and frequency of nAb‐CCL2 injections significantly suppressed tumor growth in the HFD group but not in the normal diet group." (PMID 41160815, 2026). "The HIF‐1α target genes Vegf, Snai1, and Ccng2 showed reduced expression upon nAb‐CCL2 treatment in the CD group, although this did not lead to significant tumor suppression." (PMID 41160815, 2026). "In conclusion, these experimental conditions confirm that the observed inhibition of tumor growth by nAb‐CCL2 resulted from regulation of lipid metabolism rather than immune modulation." (PMID 41160815, 2026). "In the HFD group, nAb‐CCL2 treatment significantly reduced tumor growth compared to the control IgG subgroup, while no such reduction was seen in the CD group." (PMID 41160815, 2026). "Thus, our results demonstrated that CCL2 and GM-CSF are key downstream targets of N4BP1 for establishment tumor-suppressive immune microenvironment." (PMID 41513619, 2026). "Additionally, it induces the expression of HIF-1 targets such as CCL2, CXCR4, and endothelin, which leads to the recruitment of macrophages to the tumor." (PMID 41008931, 2025). "For example, decreased CXCL9 suggested that a reduction in CD8+ CHRNA7KO tumor-infiltrating CD8+ lymphocytes (TILs) may be a recruitment defect, while increased CCL2 could be related to the recruitment of myeloid-derived suppressor cells." (PMID 40653990, 2025). "In favor of this, preclinical models involving inhibition of CCL2, NOS2, and LCN2 pathways have shown anti-tumor effects and may be explored to improve IL6 inhibitory strategies after PD-L1 treatment failure." (PMID 39663510, 2025). "We used Ccr1- and Ccr2-deficient mice and two different tumor cells lines, MC38 and LLC1 with and without Ccl2-deficiency in vitro and in vivo." (PMID 39566333, 2025). "While immunosuppressive factors such as CCL2, CXCL12, IL-4, and IL-10 sustain an immune-excluded TME, pro-inflammatory mediators like IFN-γ, TNF-α, and CXCL10 counteract these effects by promoting immune cell infiltration and tumor suppression." (PMID 40330466, 2025). "Recent research has also explored blocking the CCL2/CCR2 signaling axis, responsible for monocyte recruitment and M2 differentiation, as a promising strategy to reduce TAM infiltration in the TME and enhance anti-tumor immune responses." (PMID 40843751, 2025). "These macrophages secrete CCL2, VEGF, and arginase-1, which recruit additional suppressive myeloid cells and deplete nutrients essential for T-cell activation, thereby fostering immune escape and tumor progression in NSCLC." (PMID 41584608, 2025). "Additionally, NK cells secrete chemokines such as CCL1, CCL2, CCL3, CCL4, CCL5, and CXCL8, which contribute to the recruitment of T cells and macrophages into the TME, and tumor cell destruction." (PMID 40141437, 2025). "Further genetic ablation experiments demonstrated that c-Jun in cDCs functioned downstream of TLR7 signaling to mediate the antitumor effect of IL-12 while simultaneously inducing the secretion of CCL2, which recruited pDCs to the TME for direct tumor suppression." (PMID 40547481, 2025).
tumor (continued). "In addition, by modulating the ECM and releasing chemotactic factors including CCL2, CCL5, and CXCL12, TAM foster tumor cell migration and direct them towards blood vessels." (PMID 40725081, 2025). "Therefore, experimental designs should integrate spatial and multi-omics pharmacodynamic indicators, such as the reduction of TAM-tumor-CAF neighbor clusters, decreased TREM2 or SPP1 TAM load, and normalization of CCL2, IL10, and TGFB." (PMID 41488638, 2025). "When macrophages were treated with the CCL2 inhibitor mNOX-E36, they did not migrate toward tumor-conditioned media, confirming the necessity of CCL2 for their recruitment." (PMID 40867316, 2025). "Circulating monocytes, under the influence of chemokines like C-C motif ligand 2 (CCL2) and C-C motif ligand 5 (CCL5), are actively recruited to the tumor site, where they differentiate into macrophages and adopt pro- or anti-tumor phenotypes depending on microenvironmental cues." (PMID 40098971, 2025). "CAAs differ from “normal” adipocytes as they display fibroblast-like morphology, usually contain several dispersed small lipid droplets, and produce increased amounts of inflammatory cytokines IL-1β, IL-6, IL-8, TNF, chemokines (CCL2, CCL5), and leptin, which altogether facilitate tumor progression." (PMID 40940764, 2025). "Moreover, cytokine-driven activation of the CCL2/AKT/β-catenin axis by TAMs further potentiates CSC maintenance and tumor aggressiveness, ultimately fostering TNBC progression and resistance to therapy." (PMID 41142826, 2025). "In our study, CCL2+ macrophages emerged as significant contributors to the immunosuppressive milieu and direct enhancers of the survival and metastatic potential of PDAC tumor cells." (PMID 40092486, 2025). "Microglia also release specific chemokines, including CCL2 and CXCL10, which attract immune cells to the tumor site, though these chemokines may paradoxically contribute to an immunosuppressive tumor microenvironment under certain conditions." (PMID 39857798, 2025). "Corresponding with GeoMx data, the majority of CCL2 seemed to be expressed by stromal cells rather than tumor epithelium." (PMID 40673486, 2025). "CCl2-induced M2 polarization increases the expression of PD-L1 and PD-L2 in TAMs, which transmit inhibitory signals to CD8 + T cells through PD-1 signaling and helps tumor cells escape the attack of the immune system." (PMID 41341593, 2025). "Finally, silibinin modulates the immune microenvironment by reducing NF-κB-regulated cytokines, such as IL-6, IL-8, and CCL2, which limits TAM recruitment and dampens inflammation-driven tumor growth." (PMID 40650040, 2025). "GBM expresses CCL2 and CCL7, which facilitate tumor recruitment by CCR2+ cells." (PMID 40514725, 2025). "Through gene expression analyses of colon tissue, we identified significant increases in markers of tumor progression and microenvironment regulation, including LGR5, TWIST1, SNAIL, IL-8, CCL2, and COX2, in the colon of PSC patients compared with those with IBD alone." (PMID 40476597, 2025). "However, microglia also secrete critical cytokines such as interferon-γ (IFN- γ), IL-1, and IL-6, alongside chemokines like CCL2 and CXCL10, which modulate T cell activity and recruit immune cells to the tumor site." (PMID 39857798, 2025). "Also, F. nucleatum induced adipocyte lipolysis through CCL2 autocrine signaling, and that CCR2 inhibition also reversed this metabolic reprogramming, thereby reducing the energy supply to tumor cells." (PMID 41276817, 2025). "Additionally, chemotherapeutic agents (e.g., cisplatin) induce tumor release of oxidized phospholipids (oxPAPC), which recruit MDSCs via palmitoylation-dependent MCP-1/CCL2 and LTB4/LTB4R pathways, ultimately leading to chemoresistance." (PMID 40977744, 2025).
tumor (continued). "The results revealed that irradiation increased the levels of chemokines involved in the migration of T cells (e.g., CXCL10, CCL2, CCL3, and CCL5) but decreased the levels of proangiogenic factors (e.g., VEGF and basic FGF), which facilitate T cells infiltration into the tumor bed." (PMID 40510363, 2025). "Consistently, deletion of CCL2 in the host, rather than in tumor cells, significantly decreased TAM infiltration, angiogenesis, and lung metastasis in mouse orthotopical 4T1 tumor models." (PMID 40756366, 2025). "Consistently, elevated CCL2 levels were detected in supernatants from LCN2-high tumor cells cocultured with astrocytes but not in supernatants from tumor cells alone or from those cocultured with oligodendrocytes." (PMID 41436606, 2025). "Similarly, in lung tissue samples obtained from patients with NSCLC and a mouse NSCLC model, the authors identified tumor cells expressing high levels of TGF-β1 and CCL2, as well as Toe-Macs expressing NLRP3, IL-1β, TGF-β1, CCL2, IL-6, and PD-L1." (PMID 41178715, 2025). "Moreover, we identified several key players contributing to a pro-tumor microenvironment including OMD+ fibroblast and CCL2+ macrophage." (PMID 40092486, 2025). "Blocking CCL2 signalling significantly reduced MDSC infiltration and restored anti-tumour immunity." (PMID 40278081, 2025). "Therefore, the combination therapy with TTFields and anti-PD-1 activates STAT1 and IRF1 through ICD in tumor tissue, enhancing the CCL2/8-CCR2 axis and CXCL9/10-CXCR3 axis, which recruits CD8+ T and CD4+ T cells to infiltrate and kill tumor cells." (PMID 40098106, 2025). "Moreover, a recent study indicated that CCL2 induces macrophages to express epidermal growth factor (EGF), enhancing tumor proliferation and metastasis through the activation of the EGFR receptor." (PMID 40134607, 2025). "In addition, tumor cell‐expressed HVEM altered chemokine expression (CXCL1/9/10/11 and CCL2/4/5) and STAT signal activation (STAT5 and STAT6) in ID8 cells." (PMID 40105652, 2025). "Notably, CAF-FAP and CAF-C7 both showed upregulated chemokine signaling pathway, but showed high expression of pro-inflammatory genes (CCL2, CXCL12, GDF15, and LIFR) at tumor core and pro-fibrotic genes (TNFRSF12A, TGFBR1, TGFBR2) at FR, respectively." (PMID 39870619, 2025). "Multiplex bead-based ELISA (Luminex) analysis of cell culture supernatant from 4T1 Vector, 4T1 MerTK C8, and 4T1 MerTK C11 tumor cells revealed significantly increased release of the pro-inflammatory cytokines IL-1 alpha and IL-31, and chemokines MCP-1 (CCL2) and MCP-3 (CCL7)." (PMID 40391157, 2025). "Tumor-cell-derived CCL4 and CCL2 can enhance TAM infiltration, leading to cancer progression." (PMID 39996747, 2025). "In ENKTCL, MDSCs are recruited and activated within the tumor microenvironment (TME) by EBV- and tumor-driven factors, including GM-CSF, IL-6, TGF-β, CCL2, and CXCL8, which promote both monocytic (M-MDSC) and granulocytic (PMN-MDSC) subtypes and enhance their suppressive phenotype." (PMID 41303704, 2025). "In addition to nucleic acid drugs, small molecule drugs such as Bindarit can reduce the synthesis of CCL2 by inhibiting AKT and NF-κB pathways, showing potential inhibitory effects on tumor progression and metastasis." (PMID 41341593, 2025). "Recognizing the interplay between sCD163, which acts as a surrogate of CD-163 positive TAMs burden, with CCL2 and CCL4 that enforce TAMs’ tumor infiltration, could reveal new biomarkers." (PMID 39996747, 2025). "In the study of non-intracranial tumors, CCL2 gene transduction has been regarded as an effective vaccine strategy to enhance the host cell defense ability against tumor cell attack." (PMID 41341593, 2025). "Furthermore, in mice, CCR2, along with its ligands CCL2 and CCL7, is essential for the migration of MDSCs from the bloodstream to the tumor." (PMID 41368628, 2025).
tumor (continued). "Knocking down OSMR dramatically reduces tumor cell proliferation, invasion, and migration, accelerates cell death and cell cycle arrest, and lowers JAK and STAT3 phosphorylation as well as CCL-2 expression levels, all while decreasing the fraction of M2 macrophages." (PMID 40161370, 2025). "It is worth noting that intraperitoneal administration of a CCL2-neutralizing antibody significantly suppressed lung metastasis in our study but not primary tumor growth in orthotopic tumor model mice." (PMID 40343498, 2025). "Across multiple preclinical tumor models, RT has been shown to increase the expression of cytokines such as IL-1β, GM-CSF (CSF2), and G-CSF (CSF3), along with chemokines including CXCL1, CXCL2, CXCL5, CCL2, and CCL5." (PMID 40805288, 2025). "Other factors that are secreted by the primary tumor, such as G-CSF, angiopoietin-like protein 2 (ANGPTL2), IL-6, and CCL2, promote the expansion of the myeloid lineage, their recruitment into the lung PMN and their polarization into an immunosuppressive phenotype." (PMID 40370456, 2025). "Notably, both the neutralizing antibody targeting CCL2 and the FMD medium significantly inhibited gefitinib-induced macrophage recruitment and concurrently suppressed tumor spheroid growth." (PMID 40808689, 2025). "Moreover, our transcriptomic data further revealed that lacidipine regulated multiple immune‐related genes, significantly upregulating “hot” tumor‐related genes such as CCL5, CD274, CXCL10, and CXCL11, while downregulating the “cold” tumor‐related gene CCL2." (PMID 39585774, 2025). "Additionally, MDSCs in HR+ BC can secrete cytokines, IL-6, and chemokine ligands (CCLs) like CCL2, suppressing T-cell function and recruiting more immune-suppressive cells to the TME, reinforcing the cold tumor phenotype." (PMID 40281554, 2025). "For example, agents targeting the CCL2/CCR2 axis have shown promise in reducing the recruitment of monocyte-derived TAMs, while inhibitors of colony-stimulating factor 1 receptor (CSF1R) blunt TAM support for tumor growth." (PMID 40330466, 2025). "To further investigate the effect of OSMR mediated JAK/STAT3/CCL-2 pathway regulation on malignant behavior of GBM cells and macrophage polarization, we co cultured SF188 cells with THP-1 generated microglia to simulate the tumor microenvironment." (PMID 40161370, 2025). "In the present study, we found that after BM of BC cells, Arg1+ microglia were significantly aggregated at the site of tumor metastasis, and the levels of cytokine IL6, chemokine CCL2, were significantly increased, suggesting an immunosuppressive microenvironment following BC-BM." (PMID 40444044, 2025). "Another study showed that phytosomal curcumin exerts its therapeutic effect in GBM by inducing the release of monocyte chemoattractant protein-1 (MCP-1, also known as C-C motif chemokine ligand 2 (CCL2)), from TAMs, which in turn recruits activated NK cells to GBM, resulting in anti-tumor effects." (PMID 40453088, 2025). "Additionally, chemokines such as CXCL1, CXCL2, CXCL5, CCL2, and CCL3, produced by MAFs, play a role in attracting pro-tumor MDSCs to inhibit CD8+ cells." (PMID 40136652, 2025). "Molecular profiling of tumor tissue or exosomes for neurotrophic factors (NGF, BDNF, GDNF), chemokines (CXCL12, CCL2), or neuronal transcription factors (POU4F1) may serve as predictive biomarkers of neural involvement." (PMID 41009819, 2025). "Notably, factors such as VEGF-A and CCL2 can recruit circulating monocytes, and their expression levels positively correlate with TAM accumulation and vascular density in certain tumor types." (PMID 40936918, 2025). "Human CAF-S1 cluster strongly expresses CXCL12 and CCL2 chemokine genes; through CXCL12-CXCR4 interaction and CCL2 release CAFs may recruit monocytes into TME, thus favouring tumor progression, angiogenesis, metastasis, and low survival." (PMID 40092980, 2025).